VCL (vinculin)
Diseases named in the same sentence as VCL in open-access papers (continued):
Sharing a sentence is not in itself a finding about the gene and the disease.
irritable bowel syndrome (3 papers, 2017 to 2024). Irritable bowel syndrome (IBS) is a chronic functional condition of the lower gastrointestinal (GI) tract characterized by abdominal pain or discomfort and disordered bowel habit (diarrhea, constipation, or fluctuation between the two). "Animal models of post-infectious cdt-positive Campylobacter jejuni have demonstrated that host antibodies to CdtB cross-react with vinculin in the host gut producing an irritable bowel syndrome (IBS)-like phenotype." (PMID 28348804, 2017). "Another study found that both anti-CdtB and anti-vinculin biomarkers were elevated in subgroups, of irritable bowel syndrome with constipation (IBS-C) and IBS-D, while only anti-vinculin biomarkers were elevated in irritable bowel syndrome mixed type (IBS-M) subgroups." (PMID 38496157, 2024).
Obesity (3 papers, 2023). Accumulation of substantial excess body fat. "It suggested that the chronic inflammation in obesity might interfere with the aseptic inflammation induced by the mechanical loading by the increase of vinculin, osteopontin, and cathepsin D." (PMID 36674516, 2023).
osteoporosis (3 papers, 2023 to 2025). A condition of reduced bone mass, with decreased cortical thickness and a decrease in the number and size of the trabeculae of cancellous bone (but normal chemical composition), resulting in increased fracture incidence. "VCL is a promising marker for osteoporosis and bone loss diagnosis." (PMID 37923747, 2023). "In summary, in this study, we demonstrate that vinculin plays an important role in control of bone formation and may be a useful target for the prevention and treatment of aging and estrogen deficiency induced osteoporosis." (PMID 40796727, 2025). "Here we show that expression of FA protein vinculin is dramatically reduced in osteocytes in patients with aging-related osteoporosis." (PMID 40796727, 2025).
acute aortic dissection (2 papers, 2022 to 2023). "They suggested that vinculin could be a biomarker for aortic dissection." (PMID 36135831, 2022). "Vinculin concentrations in patients with aortic dissection but not in those with AMI were higher than in the controls." (PMID 36135831, 2022).
Brugada syndrome (2 papers, 2017 to 2022). A genetically heterogeneous condition characterized by complete or incomplete right bundle branch block accompanied by ST elevation in leads V1-V3. "Vinculin’s role in SBMA cardiac phenotypes should be considered for further research, as SBMA patients have an increased prevalence of Brugada Syndrome, a cardiac syndrome that can lead to ventricular fibrillation and early death." (PMID 35791011, 2022).
celiac disease (2 papers, 2015 to 2017). An autoimmune genetic disorder with an unknown pattern of inheritance that primarily affects the digestive tract. "In addition, it is possible that immune responses to CdtB and vinculin could vary with differing ethnic backgrounds—Asians have been shown to have differing prevalences of certain antibodies for celiac disease." (PMID 25970536, 2015). "We observe that plasma antibodies to vinculin and CdtB were elevated in D-IBS compared to healthy controls, subjects with celiac disease, and subjects with IBD such that the biomarkers appeared to be able to distinguish D-IBS from all non-IBS." (PMID 25970536, 2015). "Anti-vinculin levels were also significantly higher in D-IBS subjects (1.34±0.85) when compared to healthy subjects (0.81±0.59), Crohn’s disease (1.05±0.91), ulcerative colitis (0.96±0.77) and celiac disease (1.07±0.98) (P<0.0001)." (PMID 25970536, 2015). "Furthermore, studies in humans have confirmed that anti-CDT-B and anti-vinculin antibodies are elevated in patients with diarrhoea-predominant-IBS compared to non-IBS subjects with celiac disease or healthy controls." (PMID 28348804, 2017). "Interestingly anti-CdtB, but not anti-vinculin, was high in celiac disease as well." (PMID 25970536, 2015).
Chlamydial infection (2 papers, 2015 to 2018). "Given previous findings demonstrating the involvement of various focal adhesion components during Chlamydial infection, we sought to determine in greater detail the involvement of vinculin in Chlamydia invasion." (PMID 26649283, 2015).
COVID-19 (2 papers, 2022 to 2024). A disease caused by infection with severe acute respiratory syndrome coronavirus 2. "The high expression of VCL can enhance cellular adhesiveness, and its regulatory role in adhesion is crucial for biological processes such as leukocyte transmigration through epithelial or endothelial layers, thereby mediating the migration of leukocytes in the inflammatory response of COVID-19." (PMID 38424541, 2024).
diabetes (2 papers, 2022 to 2023). "Differential expression of proteins linked to cancer metastasis, such as the upregulation of vinculin and endoplasmin and downregulation of WWC3 and IFT88, was seen in the patients with diabetes." (PMID 35454982, 2022). "In this study, vinculin, an actin-binding protein, was found highly expressed in the endometrial cancer tissues of patients with diabetes." (PMID 35454982, 2022). "Since platelet P2Y12 signaling is activated in patients with diabetes, it is possible that under hyperglycemic environment, filamin A, which is activated by the activation of P2Y12 signaling, mediates platelet activation in concert with vinculin." (PMID 36831080, 2023). "In addition, protein changes associated with cancer metastasis, such as the upregulation of vinculin and endoplasmin, and downregulation of WWC3 and IFT88, were seen in the patients with diabetes." (PMID 35454982, 2022).
embryonal carcinoma (2 papers, 2011 to 2022). A non-seminomatous malignant germ cell tumor characterized by the presence of large germ cells with abundant cytoplasm resembling epithelial cells, geographic necrosis, high mitotic activity, and pseudoglandular and pseudopapillary structures formation. "inactivated the vinculin gene in mouse embryonal carcinoma cell lines and embryonic stem cells, and their results showed that the loss of vinculin resulted in increased cell motility." (PMID 36052248, 2022).
Ewing sarcoma (2 papers, 2015 to 2025). A small round cell tumor that lacks morphologic, immunohistochemical, and electron microscopic evidence of neuroectodermal differentiation. "Using immunofluorescence, we evaluated the presence and distribution of vinculin in Ewing sarcoma cells treated with WNT974." (PMID 41301074, 2025). "The suppression of EWS/FLI1 also leads to a selective decrease in protein expression of the Ewing sarcoma super-enhancer-associated genes CAV1 and CCND1 versus a vinculin control." (PMID 26337082, 2015). "In addition, when A4573 cells were treated with palmostatin B, immunofluorescence analysis revealed that ALCAM became more diffuse and punctate throughout the cells with a visible decrease in vinculin, suggesting that these proteins all interact in Ewing sarcoma cells." (PMID 41301074, 2025). "We demonstrate changes to FAK phosphorylation, cross-linking of filamentous actin by vinculin to ALCAM, and alterations in post-translational modifications of ALCAM, which all affect Ewing sarcoma cell migration." (PMID 41301074, 2025).
focal segmental glomerulosclerosis (2 papers, 2018 to 2022). A renal disorder characterized by sclerotic lesions in the glomeruli. "In kidney sections from patients with focal segmental glomerulosclerosis, minimal change disease and membranous nephropathy, we observed dramatic differences in the expression levels and localization of vinculin." (PMID 29241625, 2018). "Finally, in kidney biopsies from patients with focal segmental glomerulosclerosis (FSGS), minimal change disease (MCD), and membranous nephropathy (MN), marked differences were found in vinculin localization that correlated with the level of nephrin localization in capillary loops." (PMID 29241625, 2018).
glomerular disease (2 papers, 2018 to 2022). "To analyze overall vinculin localization to capillary loops in glomerular diseases, we performed ratiometric imaging, quantifying vinculin levels relative to nephrin levels specifically in nephrin-positive areas." (PMID 29241625, 2018). "Taken together, these data demonstrate that with human glomerular disease, marked differences are present in the level and localization of vinculin." (PMID 29241625, 2018). "Furthermore, vinculin protein expression was reportedly decreased in glomeruli in patients with idiopathic FSGS or membranous nephropathy, suggesting that enhanced vinculin expression in glomeruli can differentiate this disease from other glomerulopathies before gene-specific analyses." (PMID 36173685, 2022).
hepatocellular carcinoma (2 papers, 2014 to 2022). A malignant tumor that arises from hepatocytes. "Using immunoprecipitation in cultured cells of the line PLC as well as in human hepatocellular carcinoma (HCC)-lysates, we isolated E-N-cadherin heterodimers in a complex with the plaque proteins α- and β-catenin, plakoglobin, and vinculin." (PMID 36010583, 2022).
Hypertension (2 papers, 2015 to 2022). The presence of chronic increased pressure in the systemic arterial system. "Our results revealed a significant genotypic association of rs4746172 of VCL with hypertension with a lower frequency of minor allele in male subjects (OR = 0.70, 95% CI: 0.54–0.92, p = 0.011) but not in females." (PMID 26487440, 2015).
inflammatory bowel disease (2 papers, 2020 to 2021). A spectrum of small and large bowel inflammatory diseases of unknown etiology. "This allowed anti-CdtB and anti-vinculin circulating antibodies levels to be used as biomarkers to differentiate IBS-Diarrhea predominant type from inflammatory bowel disease (IBD) in different settings, with promising results." (PMID 32397332, 2020).
lung adenocarcinoma (2 papers, 2018 to 2025). A carcinoma that arises from the lung and is characterized by the presence of malignant glandular epithelial cells. "Consistent with our findings, analysis using the GEPIA2 database, which includes RNA-seq data from The Cancer Genome Atlas (TCGA) lung adenocarcinoma (LUAD) samples (483 tumor and 347 normal tissues), revealed decreased VCL expression in LUAD tissues compared to normal tissues." (PMID 40563579, 2025).
meningitis (2 papers, 2018 to 2022). A disorder characterized by acute inflammation of the meninges of the brain and/or spinal cord. "The increased expression of VCL in saliva could potentially be associated with muscle damage and seizures that usually are presented in the case of meningitis." (PMID 36430174, 2022). "However, in our study, there were specific proteins only showing changes in pigs with meningitis but not in pigs with sepsis due to LPS administration, like VCL, DSC2 or HBB." (PMID 36430174, 2022). "However, there are no reports about the relationship between clathrin/vinculin and meningitis." (PMID 29479521, 2018).
minimal change disease (2 papers, 2018 to 2025). "Mouse experiments revealed that injecting anti-vinculin antibodies or recombinant vinculin protein induced proteinuria and podocyte injury in the immunized mice, and the renal phenotype closely resembled the pathological characteristics of minimal change disease." (PMID 40463498, 2025).
nephrotic syndrome (2 papers, 2021 to 2025). A collection of symptoms that include severe edema, proteinuria, and hypoalbuminemia; it is indicative of renal dysfunction. "Our findings highlight the potential pathogenic role of anti-vinculin autoantibodies in podocyte injury in INS, supporting the broader hypothesis that certain forms of nephrotic syndrome may represent antibody-driven autoimmune diseases." (PMID 40463498, 2025). "Patients who were positive for anti-vinculin autoantibodies (n = 80) predominantly exhibited severe nephrotic syndrome, characterized by significantly higher urinary protein/creatinine ratio, lower serum albumin levels, and increased serum cholesterol and CD19 levels." (PMID 40463498, 2025).
osteosarcoma (2 papers, 2019 to 2021). A usually aggressive malignant bone-forming mesenchymal neoplasm, predominantly affecting adolescents and young adults. "TIRF time-lapse imaging of a migrating human osteosarcoma (U2OS) (A) and mouse embryonic fibroblast (MEF) cell (B) expressing LifeAct-TagGFP2 (gray) and vinculin-mApple (magenta)." (PMID 33506761, 2021). "Vinculin, as F-actin, also does not co-localize with AnxA6 in mineralizing osteosarcoma Saos-2 cells." (PMID 31212828, 2019).
Renal neoplasm (2 papers, 2008 to 2023). The presence of a neoplasm of the kidney. "Various fusion genes have been identified in recent years, such as VCL, TPM3, EML4, STRN, and HOOK1, with renal tumors of VCL and HOOK1 rearranged with ALK only described in pediatric patients." (PMID 37367052, 2023).
renal oncocytoma (2 papers, 2009 to 2017). "Vinculin was weakly positive in only 2 out of 15 cases of chromophobe RCC, and single case of collecting duct RCC and was negative in all cases of clear cell renal cell carcinoma, papillary renal cell carcinoma and renal oncocytoma." (PMID 19558708, 2009).
squamous cell carcinoma (2 papers, 2014 to 2015). A carcinoma arising from squamous epithelial cells. "Vinculin, an adhesion protein that participates in cell-cell adhesions and that is inversely correlated with the metastatic potential of human squamous cell carcinomas, was significantly downregulated in all LKB1-attenuated ICCs." (PMID 26056085, 2015).
teratocarcinoma (2 papers, 2012 to 2019). A germ cell tumor characterized by the presence of an embryonal carcinoma component and a teratoma component. "Since the formation of TJs is reported to be affected by vinculin KO in mouse teratocarcinoma F9 cells, we examined vinculin’s role in the TJ’s paracellular barrier function by generating vinculin KO Eph4 cells (mammary epithelial cells) using the CRISPR-Cas9 system." (PMID 31399484, 2019). "Interestingly, silencing of vinculin expression in F9 embryonic teratocarcinoma cells, another cell model closely related to stem cells, has shown increased resistance to anoikis, while ectopic reexpression of vinculin restored sensitivity to anchorage-dependent survival." (PMID 22988499, 2012).
triple-negative breast carcinoma (2 papers, 2021 to 2023). An invasive breast carcinoma which is negative for expression of estrogen receptor (ER), progesterone receptor (PR), and human epidermal growth factor receptor 2 (HER2). "In triple negative breast cancer cells reduction of tumorigenic phenotypes is accompanied by reduced expression of RAC1, alpha-actinin, vinculin and FAK65 and silencing of vinculin reduces cell viability and decreases tumor volume in animal models." (PMID 33633298, 2021).
Ventricular arrhythmia (2 papers, 2018 to 2025). "Studies on mouse models hypothesized that variants in VCL may increase the risk for cardiac conduction defects associated with ventricular arrhythmia without obvious structural heart disease and may account for some cases of sudden arrhythmic death syndrome (SUNDS)." (PMID 39940965, 2025).
abdominal aortic aneurysm (1 paper, 2021). Enlargement and ballooning of the vessel that supplies arterial blood to the abdomen, pelvis and legs. "VCL is believed to be related to the formation of abdominal aortic aneurysm 43 and showed a decreasing trend in aneurysm protein spectrum in our study." (PMID 33389819, 2021).
AIDS (1 paper, 2010). A syndrome resulting from the acquired deficiency of cellular immunity caused by the human immunodeficiency virus (HIV). "For example, the host protein interaction net such as VCL - TLN1 - actin, cytoplasmic 2(ACTG1) - FLNA was found to interact with nef and pol (HIV function proteins), and be substantially up-regulated in HIV/AIDS patients." (PMID 20222986, 2010).
aneurysm (1 paper, 2021). Bulging or ballooning in an area of an artery secondary to arterial wall weakening. "We found several proteins whose expression levels were significantly different, such as MYLK, VCL, and collagen type IV, in both rabbit and human aneurysms, suggesting that these proteins may be vital in the development of aneurysms." (PMID 33389819, 2021). "The protein expression levels of COL4A2, MYLK, and VCL were decreased after SMCs were intervened with TNF‐α, consistent with the results from mass spectrometry on aneurysm samples (E‐G)." (PMID 33389819, 2021). "We found that COL4A2, MYLK, VCL, and TAGLN may be related to aneurysm development." (PMID 33389819, 2021).
asthma (1 paper, 2017). "Importantly, ADAM33 expression positively correlated with cell traction force, stiffness, and expression of F-actin and vinculin, suggesting that ADAM33 is a mediator of ASM cell dysfunction in asthma." (PMID 28056993, 2017).
Autoimmunity (1 paper, 2015). The occurrence of an immune reaction against the organism's own cells or tissues. "Based on the pathophysiologic observations in this animal model of C. jejuni infection, we hypothesized that exposure to CdtB led to detectable immunity to CdtB and autoimmunity to vinculin based on molecular mimicry." (PMID 25970536, 2015).
Blindness (1 paper, 2016). Blindness is the condition of lacking visual perception defined as a profound reduction in visual perception. "These along with vinculin can be used for early diagnosis and management of AMD, which is essential for preventing blindness in elderly populations that have limited access to retinal examination services." (PMID 27605007, 2016).
bone cancer (1 paper, 2019). A primary or metastatic malignant neoplasm affecting the bone or articular cartilage. "First, through FRAP-experiments we examined the binding dynamics of fluorescently-labelled paxillin, vinculin, VASP and zyxin at FAs in two different cell-types from two different species; U2OS cells, a human bone cancer cell line, and MDCK dog kidney cells." (PMID 31320676, 2019).
breast tumor (1 paper, 2017). "In addition, nuclear calcium buffering regulates breast tumor cell motility, culminating in less cell invasion, likely due to enhanced vinculin expression, a focal adhesion structural protein." (PMID 28376104, 2017).
Cerebral ischemia (1 paper, 2025). Restriction of arterial blood supply to the brain associated with insufficient oxygenation to support the metabolic requirements of the tissue. "Furthermore, our findings revealed additional proteins that may serve as biomarkers for cerebral ischemia-reperfusion injury, including STAT3, NME2, VCL, and CCT3." (PMID 39936033, 2025).
colon adenocarcinoma (1 paper, 2021). "Furthermore, it was shown that GSN colocalizes with vinculin and actin, orchestrating cell migration and podosome formation in the colon adenocarcinoma cell line." (PMID 34685680, 2021).
coronary artery spasm (1 paper, 2025). "SELENBP1 (selenium-binding protein 1) and vinculin (VCL) were recently analyzed in cases of death caused by coronary artery spasm, proving their reliability in such instances." (PMID 40725061, 2025).
dengue virus infection (1 paper, 2021). "A low expression of moesin, alterations to actin stress fibers, and a dot-like structural formation of vinculin are responsible for the cellular permeability changes of human ECs during dengue virus infection and TNF-α induction." (PMID 34696472, 2021).
Desminopathies (1 paper, 2022). "Finally, we examined the expression level and localization of vinculin in muscle from patients with desminopathies and adult controls." (PMID 35350386, 2022).
dysentery (1 paper, 2013). Acute inflammation of the intestine associated with infectious diarrhea of various etiologies, generally acquired by eating contaminated food containing toxins, biological derived from bacteria or other microorganisms. "In the case of S. flexneri, a leading cause of dysentery worldwide, the entry into human epithelial cells is dramatically impaired in the absence of vinculin." (PMID 23294665, 2013).